FGF19 (fibroblast growth factor 19)
Diseases named in the same sentence as FGF19 in open-access papers (continued):
Sharing a sentence is not in itself a finding about the gene and the disease.
tumor (continued). "This important hormone-like regulator was not investigated in this study, yet others have shown that serum FGF19 was increased in patients with NASH-HCC and associated with tumor markers and with NAFLD progression." (PMID 34943104, 2021). "Abnormal gene expression of FGFR4 with its ligand FGF19 has been determined as a vital factor in tumor growth." (PMID 33981224, 2021). "When examining in vivo and chemically induced liver tumor models, it was observed that the FGF19 antibody suppressed tumor growth." (PMID 33981224, 2021). "The result suggests that inflammatory cytokines, especially IL-1β, can influence the activation of the FGF19/FGFR4 signaling pathway in the tumor microenvironment." (PMID 33981224, 2021). "FGF401 can act synergistically with vinorelbine to inhibit tumor growth and promote tumor apoptosis by inhibiting the FGF19/FGFR-4 signaling pathway." (PMID 34724890, 2021). "Our study demonstrated that robust inhibition of FGF19/FGFR4 is of importance for the exertion of anti-tumor effects by MKIs." (PMID 33674622, 2021). "The results also showed that inhibiting the mechanistic target of rapamycin (mTOR) in the in vivo LSQ models overexpressing FGF19, was an effective way to inhibit the tumor." (PMID 34572066, 2021). "Emerging data in HCC studies implicate that aberrant expression of FGF19 and FGFR4 lead to tumor proliferation, thereby causing HCC." (PMID 34572066, 2021). "Later, studies by the same group demonstrated for the first time that overexpression of FGF19 enhanced tumor cell proliferation and metastasis in an in vivo model of LSQ." (PMID 34572066, 2021). "We have demonstrated that blockade of tumor-derived FGF19/FGFR4 signaling represents a promoting therapeutic strategy to preferentially target FGF19-driven HNSCC." (PMID 33691750, 2021). "Administration of FGF19 led to increases in hepatocellular proliferation which preceded tumor development." (PMID 35116006, 2021). "FGF19 is expressed in approximately one-third of HCC tissue samples and is associated with tumour aggressiveness, represented by a poorly differentiated tumour and an unfavourable prognosis." (PMID 34944930, 2021). "IHC analysis of Ki-67 expression revealed that a remarkable increase of proliferation in tumor and lung of the FGF19-OE groups, along with high serum levels of FGF19." (PMID 32111983, 2020). "Using a subcutaneous model, a marked increase in tumor size was observed in mice receiving FGF19-OE lentivirus compared with those receiving the control lentivirus in SK-MES-1 cells." (PMID 32111983, 2020). "Higher expression of FGF19 in HCCs promotes tumor cell survival and has antiapoptotic effects that are exerted through the FGFR4-glycogen synthase kinase (GSK)3β-Nrf2 signaling cascade." (PMID 32104677, 2020). "The oral administration of 30 mg/kg FGF401 twice a day was effective against all 9 models that expressed high levels of FGF19, as indicated by the fold change in tumor volume at the end of treatment." (PMID 33235319, 2020). "It is important to consider that FGF19/FGFR-4 signaling can alter the tumor microenvironment by modulating circulating endothelial cells via FGF19-dependent paracrine mechanisms and possibly soluble factors." (PMID 33235319, 2020). "Conversely, FGF401 did not prolong the survival of mice bearing low FGF19-expressing HCC13-0109 tumors (p = 0.6722), indicating that FGF401 conferred a survival benefit in high FGF19 tumor-bearing mice." (PMID 33235319, 2020). "In the context of FGF19-dependent tumors, FGF19/FGFR-4 blockade with FGF401 resulted in tumor growth inhibition, reduction of cell proliferation, induction of apoptosis, and improved OS in both orthotopic and ectopic models." (PMID 33235319, 2020). "In all high FGF19-expressing models, the addition of vinorelbine inhibited tumor growth more completely than did FGF401 and vinorelbine treatment alone." (PMID 33235319, 2020).
tumor (continued). "By contrast, serum FGF19 levels were higher in patients with NASH-HCC and associated with tumor markers as well as an attenuation of BA synthesis." (PMID 32352707, 2020). "FGF19 plays an important role in the proliferation of both, tumor cells and endothelial cells; therefore, it is believed to be promising therapeutic target molecules." (PMID 31718608, 2019). "In the preclinical trial phase, BLU9931 exhibited potent antitumor activity in mice with an HCC tumor xenograft with amplified FGF19 and high expression of FGF19 at the mRNA level." (PMID 31167419, 2019). "After determining of the optimal cut-off value based on the receiver operating characteristic curves (ROC), we compared the tumor detection ability of FGF19 and the existing markers." (PMID 31718608, 2019). "In our previous study, we found that FGF19 was significantly increased in both serum and tumor tissue of HCC patients." (PMID 29973237, 2018). "In contrast, genetic ablation of Il6 resulted in a significant decrease in FGF19-induced tumour multiplicity, tumour size and glutamine synthetase-positive tumour area." (PMID 28508871, 2017). "Among the top five most hyper-methylated promoters, FGF19 is related to HCC tumor promotion, FGF4 is related to HCC drug response, and HLX is involved in normal liver development." (PMID 28938868, 2017). "In contrast, tumour incidence, tumour multiplicity and tumour size were all markedly reduced in age-matched Stat3ΔHep mice, even after 12 months of continuous exposure to FGF19." (PMID 28508871, 2017). "In summary, these results indicate that IL-6 produced in the liver microenvironment is important for tumour development initiated by FGF19." (PMID 28508871, 2017). "Previous studies have shown that fibroblast growth factor 19 (FGF19) expression correlates with tumor progression and poor prognosis of HCC." (PMID 28069043, 2017). "We observed completely healthy livers free of tumours when FGF19-expressing Mdr2−/−mice were treated with anti-IL-6, whereas those treated with isotype control antibodies develop HCC." (PMID 28508871, 2017). "In future work, we will collect the tumor samples from patients with sorafenib-sensitive or resistant HCC to explore clinical importance of the FGF19/FGFR4 axis." (PMID 28069043, 2017). "Our analysis of the TCGA database revealed relatively high frequencies of FGF19 gene amplification in a variety of tumours." (PMID 28508871, 2017). "In our previous work, we have provided evidence that FGF19 secreted from either HCC cells or tumor microenvironment can activate its specific receptor FGFR4 on the surface of HCC cells." (PMID 28069043, 2017). "No mutations or homozygous deletions were detected in the FGF19 in TCGA LIHC (liver hepatocellular carcinomas) data set; one hundred per cent of the genetic alterations in FGF19 detected in these tumours were identified as gene amplifications." (PMID 28508871, 2017). "Inhibition of the FGFR4/FGF19 signaling induces tumor-specific cell death in cancer cells that express them." (PMID 27192118, 2016). "From existing data it seems that patients with tumours with detectable expression of FGF19, FGFR4 and Klothoβ would benefit from such an approach and approximately one third of all patients with HCC are expected to meet these criteria." (PMID 28943626, 2015). "Univariate and multivariate analyses revealed that the tumor FGF19 mRNA expression was an independent prognostic factor for overall and disease-free survival." (PMID 22309595, 2012). "We also measured liver weights to evaluate tumor burden because this parameter was previously shown to strongly correlate with percent tumor volume in the FGF19-TG model." (PMID 22615798, 2012). "To test the role of the FGF19/FGFR4 system in tumor progression, we used recombinant FGF19 protein and small interfering RNA (siRNA) of FGF19 and FGFR4 to regulate their concentrations." (PMID 22309595, 2012).
tumor (continued). "We decided to assess the long term effect with respect to tumor formation of sustained expression of FGF19 and FGF19-7 using AAV as a gene delivery vehicle." (PMID 22457778, 2012). "On the other hand, ectopic expression of FGF19 in mice promotes hepatocyte proliferation, hepatocellular dysplasia, and neoplasia." (PMID 22309595, 2012). "For statistical analysis of FGF19 levels, the specimens were divided into two groups based on the median value of tumor FGF19 mRNA (5.7 × 10-4): a high expression group (n = 20) and a low expression group (n = 20)." (PMID 22309595, 2012). "FGF19, acting as a core regulator of cellular metabolism, may coordinate the alterations in tumor cell metabolic pathways, thereby promoting their rapid growth and survival." (PMID 41328353, 2026). "Further analysis demonstrated that the expression of FGF19 was colocalized with markers of cholangiocytes, suggesting that FGF19 may regulate the proliferation of tumor cells through a cholangiocytic differentiation pathway." (PMID 41328353, 2026). "High expression of FGF19 is not only associated with increased clonogenicity and stem cell-like properties of GBM cells, but also with enhanced tumor invasiveness, mediated by alterations in cell adhesion and activation of the integrin signaling pathway via FGFR4." (PMID 41328353, 2026). "Future investigations are warranted to explore the intersection of FGF19-mediated mitochondrial alterations and oncogenic pathways, as such studies may offer novel strategies for targeting tumor metabolism and improving outcomes in cancer therapy." (PMID 41328353, 2026). "Therefore, FGF19 is considered a significant factor in tumor progression and immune evasion, representing a potential target for immunotherapeutic strategies." (PMID 41328353, 2026). "Targeting FGF19 holds therapeutic potential for modulating tumor metabolism by inhibiting the FGFR4-ERK pathway, thereby reducing the expression of key fatty acid synthesis enzymes, such as FASN and ACC, and ultimately disrupting the metabolic support for tumor proliferation." (PMID 41328353, 2026). "FGF19 may also impact tumor metabolism through the activation of AMPK, a key sensor of cellular energy status." (PMID 41328353, 2026). "This suggests that in KRAS-mutant PDAC, tumor progression and stromal formation may be further promoted by FGF19 through its synergistic action with HMGA1." (PMID 41328353, 2026). "Furthermore, the dysregulation of the FGF19-KLB axis in the tumor microenvironment also plays a significant role in the progression of HNSCC." (PMID 41328353, 2026). "By targeting FGF19, key aspects of tumor biology may not only be addressed, but also personalized treatment options for patients with specific molecular alterations may be offered, potentially improving prognosis in this aggressive cancer." (PMID 41328353, 2026). "FGF19 is integral to the enhancement of tumor cells' invasion and metastasis capabilities." (PMID 41328353, 2026). "Moreover, the FGF19/FGFR4 signaling pathway influences the polarization state of macrophages, promoting the M2 polarization of tumor-associated macrophages (TAMs)." (PMID 41328353, 2026). "Irpagratinib exhibited significant anti-tumor activity in HCC patients with FGF19 overexpression." (PMID 41328353, 2026). "In this review, discuss the molecular mechanisms by which FGF19 shapes tumor biology, evaluate the current status of therapeutic strategies targeting the FGF19-FGFR4 axis, and explore future opportunities such as rational drug combinations and metabolic intervention." (PMID 41328353, 2026). "Moreover, an in vivo experiment evaluated the anti-tumor effect of the FGF19-neutralizing antibody 1A6 in a mouse model of 11q13.3-amplified HCC using Huh-7 cells." (PMID 41328353, 2026).
tumor (continued). "In addition, scRNA-seq analysis revealed significant differences in FGF19 expression levels among various tumor cell subpopulations, with these differences closely associated with the proliferative capacity of tumor cells." (PMID 41328353, 2026). "Additionally, tumor metabolism can be synergistically boosted by FGF19's interactions with other oncogenes, underscoring its potential as a target for cancer therapy." (PMID 41328353, 2026). "It suggests that FGF19 exhibits tumor-promoting characteristics under certain circumstances, particularly in mouse models, where prolonged high-level expression might increase the risk of HCC." (PMID 41328353, 2026). "Fisogatinib resulted in 17% ORR (1 CR and 10 PR) in 66 FGF19-positive tumours." (PMID 40205008, 2025). "Forty-one percent of IHC FGF19-positive patients had a radiographic tumour size reduction." (PMID 40205008, 2025). "In HNSCC, secreted FGF19 levels were correlated with FGF19 expression in tumours." (PMID 37782406, 2024). "Thus, the embryonic biliary lineage program cooperates with stabilized nuclear β-catenin, inducing FGF19 as a paracrine growth signal that promotes tumor cell proliferation, together with active Wnt signaling." (PMID 39567523, 2024). "This suggested that the FGF19-expressing, cholangiocytic tumor cells might have a selective advantage in our culture system over passages." (PMID 39567523, 2024). "Similarly, the incidence of tumor development in FGF19/CCND1/sgTrp53 animals 10 months after HGT remained identical to that of FGF19 animals (n = 2/5, maximum of 1 tumor/liver)." (PMID 38228803, 2024). "In NPC, MSC-derived exosomes are associated with elevated expression of fibroblast growth factor (FGF)-19, enhancing tumour growth, migration, and metastasis through the activation of the FGF19-fibroblast growth factor receptor 4 (FGFR4)-dependent ERK signaling cascade and promotion of EMT." (PMID 39450176, 2024). "Similarly, FGF19 expression in tumor cells is required for enrollment in the ongoing study evaluating futibatinib." (PMID 39267840, 2024). "In PDAC models, FGF19 promotes tumor growth and stroma formation." (PMID 36919699, 2023). "Silencing either HMGA1 or FGF19 disrupts phenotypes required for tumor progression." (PMID 36919699, 2023). "We therefore reassessed FGF19 levels in these tumors and noted a marked increase in FGF19 relative to the injected pool, suggesting that escape from FGF19 silencing allowed enhanced tumor growth." (PMID 36919699, 2023). "Because our primary goal is to identify actionable mechanisms in PDAC, we determined whether targeting the HMGA1/FGF19 pathway with BLU9931 mitigates tumor and stroma formation." (PMID 36919699, 2023). "This discrepancy between in vitro and in vivo experiments indicated that FGF19 could promote CRLM through mechanisms other than tumor cell regulation via FGFR4." (PMID 37345586, 2023). "Upon endoplasmic reticulum stress, amplified FGF19 promotes tumor cell proliferation through activating fibroblast growth factor (FGF) receptor 4 (FGFR4)-glycogen synthase kinase-3beta (GSK3β)-nuclear factor erythroid-2-related factor-2 (Nrf2) signaling in hepatocellular carcinoma." (PMID 36751636, 2023). "Tumor‐secreted FGF19 mediates the polarization of hepatic stellate cells to inflammatory cancer‐associated fibroblasts (iCAFs), thereby modulating neutrophil infiltration and the metastasis‐supporting neutrophil extracellular traps (NETs) in liver metastatic niches." (PMID 37345586, 2023). "While we could not dissect the contribution of the stroma in isolation, our models suggest that HMGA1 and FGF19 collaborate to promote tumor progression and stroma formation." (PMID 36919699, 2023). "In a first-in-human study with BLU-554 in patients with HCC, the ORR was 17% in FGF19-positive patients (median duration of response: 5.3 months [95% CI: 3.7-not reached]) and 0% in FGF19-negative patients, showing a correlation between tumor response and FGF19 expression." (PMID 35655320, 2022).
tumor (continued). "Preclinical studies demonstrated that inhibition of FGF19 signalling may play a role in the anti-tumour effects of TKIs against HCC." (PMID 34944930, 2021). "FGF2 and FGF19, seem to be involved in maintaining cancer stem-like cells (CSCs) with CD44High/CD133High cell membrane markers, which play a central role in the tumor microenvironment, potentially enhancing HCC tumorigenesis, metastasis, and anticancer drug resistance." (PMID 33802841, 2021). "Primary HCC tissues consist of tumor cells with varying expression of FGF19/FGFR4." (PMID 33674622, 2021). "FGF19 knockdown suppressed xenograft tumor growth derived from knockdown control MT-LE cells." (PMID 33691750, 2021). "However, IHC data from this cohort rendered that patients with high concentrations of serum MT had significantly higher FGF19 protein levels in tumor tissues than those with low concentrations of serum MT." (PMID 33691750, 2021). "Together, inhibition of FGF19/FGFR4 signaling may play a role in the anti-tumor effects of MKIs against HCC." (PMID 33674622, 2021). "Furthermore, FGF19 protein expression in HCC tissues is significantly related to larger tumor size, advanced disease stage, and early recurrence." (PMID 33935756, 2021). "Moreover, FGF19 expression correlates with a poor prognosis, recurrence, tumor progression, and short OS5,10." (PMID 33235319, 2020). "By contrast, as an important mediator of BA metabolism and key messenger between the gut and liver, elevated FGF19 levels were associated with tumor and cell-death markers in HCC, independent of fibrosis assessment." (PMID 32352707, 2020). "FGF401 induces tumor regression in high FGF19-expressing HCC models by modulating FGF19/FGFR-4 signaling, inhibiting proliferation, inducing apoptosis, and inhibiting hypoxia via blood vessel normalization, and this effect was further enhanced by the addition of vinorelbine." (PMID 33235319, 2020). "The patient was treated with 8 mg Lenvatinib, which resulted in serum FGF19 increasing significantly (ratio: 4.10) and Ang-2 decreasing (ratio 0.37) at 4 weeks, reduction of tumor volume and a partial therapeutic response (PR) according to mRECIST guidelines using CT images after 8 weeks (b)." (PMID 31991869, 2020). "Indeed, we discovered that inhibiting mTOR in FGF19-overproducing LSQ resulted in significant tumor inhibition." (PMID 32111983, 2020). "FGF19 functions as a tumor marker for HCC detection, especially for small HCC." (PMID 31718608, 2019). "FGF19/FGFR4 inhibition is thought to lead to anti-tumor activities." (PMID 31167419, 2019). "Upregulated expression of various canonical FGFs (including FGF1, FGF2, and FGF 6–9) derived from tumor cells or stromal cells induces tumor progression in various cancers; however, the effects of circulating hormone-like FGFs (such as FGF19, FGF21, and FGF23) on tumors are unclear." (PMID 31408968, 2019). "In contrast, genetic ablation of Fgfr4 eliminated FGF19-induced tumor formation." (PMID 30679232, 2019). "Similarly, stimulation of tumor malignancy by PXR via the activation of the fibroblast growth factor 19 (FGF19) was reported." (PMID 29470550, 2018). "Il6 deficiency also reduced hepatic mRNA levels of Stat3 target genes (Birc5, Bcl2l1 and Ccnd1), cyclins (Ccna2, Ccnb1, Ccnb2), and markers of proliferation (Mki67) and HCC (Afp) in livers from FGF19-expressing mice, further demonstrating the role of IL-6 in mediating FGF19-driven tumour growth." (PMID 28508871, 2017). "Notably, treatment with tofacitinib significantly reduced the number of macroscopically detectable tumours and average tumour load in FGF19-expressing mice." (PMID 28508871, 2017). "To test whether tofacitinib can inhibit FGF19-dependent tumour formation, we injected db/db mice with AAV-FGF19, and 4 weeks later, began administration of tofacitinib in the diet." (PMID 28508871, 2017).